NCF1 (neutrophil cytosolic factor 1)
Diseases named in the same sentence as NCF1 in open-access papers (continued):
Sharing a sentence is not in itself a finding about the gene and the disease.
osteoporosis (2 papers, 2010 to 2016). A condition of reduced bone mass, with decreased cortical thickness and a decrease in the number and size of the trabeculae of cancellous bone (but normal chemical composition), resulting in increased fracture incidence. "Here, we investigated the role of reactive oxygen species in ovariectomy-induced osteoporosis in mice deficient in Ncf1, a subunit for the NADPH oxidase 2 and a well-known regulator of the immune system." (PMID 27829407, 2016).
periodontitis (2 papers, 2021 to 2024). An acute or chronic inflammatory process that affects the tissues that surround and support the teeth. "Similarly, there was significant difference in the intercellular communications between NCF1+ IM and NCF1− IM in patients with T2D and periodontitis." (PMID 39544234, 2024). "In patients with periodontitis, we observed that NCF1+ IM exhibited richer intercellular communication than NCF1− IM." (PMID 39544234, 2024). "Consequently, we identified NCF1 as core therapeutic targets for T2D and LRRC25 for T2D and periodontitis." (PMID 39544234, 2024). "Finally, we identified NCF1 as the core therapeutic target for T2D (OR = 1.09, 95% CI: 1.03-1.14, p = 1.85 ×10−3) and LRRC25 for T2D (OR = 0.96, 95% CI: 0.93-0.99, p = 3.44 ×10−2) and periodontitis (OR = 0.92, 95% CI: 0.84-0.99, p = 4.45 ×10−2)." (PMID 39544234, 2024).
renovascular hypertension (2 papers, 2013 to 2015). High blood pressure secondary to renal artery stenosis. "We found that the development of renovascular hypertension in RAS mice was associated with a rapid induction of Ncf1 and Ncf2, which encode the NADPH oxidase subunits p47phox and p67phox, respectively." (PMID 24025423, 2013).
silicosis (2 papers, 2022 to 2024). Silicosis is a respiratory disease caused by breathing in (inhaling) silica dust. "In the present study, lungs of rat model of silicosis showed increased phagocyte NADPH oxidase activity with upregulated five structural components NOX2 (CYBB), p22phox (CYBA), p47phox (NCF1), p67phox (NCF2) and p40phox (NCF4)." (PMID 34991559, 2022).
Splenomegaly (2 papers, 2022 to 2025). Abnormal increased size of the spleen. "However, administration of 1,3–1,6-β-glucan induced splenomegaly, which was severely enhanced in mice with a loss of function mutation (m1j) in Ncf1 (Ncf1*/*), with and without aCol2 antibodies." (PMID 35551269, 2022).
staphylococcus aureus infection (2 papers, 2021 to 2022). An infectious process in which the bacteria Staphylococcus aureus is present. "High expression of NCF1 was associated with adaptive immune response (BP category), immunological synapse (CC category), MHC protein binding (MF category), and Staphylococcus aureus infection (KEGG category)." (PMID 34708124, 2021).
steatosis (2 papers, 2014 to 2022). Increased lipid within the cytoplasm of cells. "Genetic deletion of the Ncf1 gene in neutrophils ameliorates chronic-plus-binge ethanol-induced liver ROS, inflammation, and steatosis." (PMID 35838051, 2022). "Our data revealed that the deletion of the Ncf1 gene in myeloid cells markedly ameliorated hepatic ROS production, steatosis, and inflammation in the chronic-plus-binge ethanol-feeding model." (PMID 35838051, 2022). "Neutrophil-specific NCF1 promotes alcohol-induced steatosis by inhibiting hepatic SIRT1 and AMPK activation." (PMID 35838051, 2022). "Our data provide a mechanistic insight into the role of neutrophils in ALD, suggesting that neutrophilic NCF1-dependent ROS generation promotes steatosis and hepatic inflammation by inhibiting AMPK and miR-223, respectively." (PMID 35838051, 2022). "To study specifically the mechanisms related to Neuhi in AH patients and liver injury, we used the mouse model of chronic-plus-binge ethanol feeding and found that myeloid-specific deletion of the Ncf1 gene abolished ethanol-induced hepatic inflammation and steatosis." (PMID 35838051, 2022). "RNA-Seq analysis revealed the AMPK pathway is one of the top pathways inhibited by neutrophilic NCF1-generated ROS, which may contribute to steatosis development." (PMID 35838051, 2022). "Role of neutrophilic NCF1/SIRT1/AMPK in alcohol-induced steatosis in AH." (PMID 35838051, 2022).
Williams syndrome (2 papers, 2025). "Although our data are correlative, these findings suggest that Ncf1 haploinsufficiency modulates ROS-driven vascular remodeling processes in both heart and brain, potentially influencing the structural and functional phenotypes associated with Williams syndrome." (PMID 41292695, 2025). "This is of interest as there is a gene dosage effect of NCF1 on the manifestation of cardiovascular symptoms in patients with Williams syndrome." (PMID 41292695, 2025). "Both most prevalent forms of Williams syndrome include ELN deletion, but NCF1 is only affected in the longer deletion." (PMID 41292695, 2025).
alcoholic steatohepatitis (1 paper, 2022). "An increase in hepatic NCF1 expression and neutrophil-related genes in patients with alcoholic steatohepatitis." (PMID 35838051, 2022). "We next asked whether the expression of hepatic NCF1 was also increased in patients with alcoholic steatohepatitis; this was determined by performing immunofluorescence staining for the presence of inflammatory cells." (PMID 35838051, 2022).
allergic asthma (1 paper, 2021). A asthma with a basis in a pathological type I hypersensitivity reaction. "However, the role of Ncf1 in allergic asthma remains unclear." (PMID 34970267, 2021).
anemia (1 paper, 2025). A reduction in the number of red blood cells, the amount of hemoglobin, and/or the volume of packed red blood cells. "Ncf2 indirectly promotes osteoclast differentiation, and mutations in Ncf2 or Ncf1 are correlated with chronic granulomatosis (CGD), a genetic disorder often accompanied by anemia." (PMID 40574855, 2025).
atherosclerotic heart disease (1 paper, 2022). "Moreover, BaP-induced NCF1/p47(phox) expression enhances superoxide anion production in an AhR-dependent manner in PMA-treated human macrophages; regulation of NCF1/NADPH oxidase by such PAHs may be involved in atherosclerotic heart disease associated with vascular disease such as sclerosis." (PMID 35990352, 2022).
autoimmune uveitis (1 paper, 2020). An autoimmune form of uveitis (disease). "We used ROS-deficient (Ncf1−/−) mice to investigate the role of ROS in experimental autoimmune uveitis (EAU)." (PMID 32380695, 2020).
avian influenza (1 paper, 2018). Infection of domestic and wild fowl and other birds with influenza A virus. "For example, the Ncf1/NADPH oxidase complex in neutrophils also significantly contributes to ROS and oxidation of phospholipids in lungs insulted with H5N1 highly pathogenic avian influenza (HPAI)." (PMID 30486363, 2018).
cervical squamous cell carcinoma (1 paper, 2024). A squamous cell carcinoma arising from the cervical epithelium. "By immunofluorescence using anti-NCF-1 antibody, BxPC-3 (as a representative PDAC line), HSC-58 (as a representative gastric adenocarcinoma line), and HeLa (as a representative uterine cervical squamous cell carcinoma line) were robustly expressing NCF-1." (PMID 39666242, 2024).
Down syndrome (1 paper, 2021). "Down syndrome (DS) and Williams-Beuren syndrome (WBS) are two well-known conditions in which chromosomal alteration affects genes involved in the regulation of the redox state, such as Cu/Zn superoxide dismutase 1 (SOD-1) and neutrophil cytosolic factor 1 (NCF-1), respectively." (PMID 34073948, 2021).
dysplasia (1 paper, 2018). A usually neoplastic transformation of the cell, associated with altered architectural tissue patterns. "Ncf1 mice with only a 7-day exposure to DSS followed by a 14-day resting period developed colonic distal high-grade dysplasia in contrast to the low-grade dysplasia found in the colon of WT mice." (PMID 29867918, 2018). "We show that Ncf1 mice lacking ROS production developed colonic distal high-grade dysplasia after a single 7-day exposure to 3% DSS in drinking water followed by a 14-day resting period, in contrast to the low-grade dysplasia in the colon of ROS-competent WT mice." (PMID 29867918, 2018).
Erythema (1 paper, 2014). Redness of the skin, caused by hyperemia of the capillaries in the lower layers of the skin. "Skin lesions were more and less severe in terms of erythema, scaling and thickness (PASI score) in Ncf1−/− and GPx1−/− mice, respectively." (PMID 24608112, 2014).
Fanconi anemia (1 paper, 2023). Fanconi anemia (FA) is a hereditary DNA repair disorder characterized by progressive pancytopenia with bone marrow failure, variable congenital malformations and predisposition to develop hematological or solid tumors. "Among these genes were members of the Fanconi anemia (FA) core complex (Fanca, Fancc, and Fancl), Rad51, Mlh1, Atrip, and Rfc2; all were expressed at significantly higher levels in Ncf1–/– vs. WT NSCs." (PMID 36707536, 2023).
gastric adenocarcinoma (1 paper, 2024). "IHC employing an anti-NCF-1 antibody revealed staining for endogenous NCF-1 in the cytoplasm of gastric adenocarcinoma cells as well as in inflammatory cells, including neutrophils, lymphocytes, and macrophages (six representative positive cases)." (PMID 39666242, 2024). "Abundant expression of NCF-1 was observed in pancreatic adenocarcinoma (PDAC) lines and in patient tissues, as well as in gastric adenocarcinomas." (PMID 39666242, 2024).
gastric cancer (1 paper, 2024). A primary or metastatic malignant neoplasm involving the stomach. "Here, we report expression of NCF-1 in pancreatic and gastric cancers, and demonstrate its biological significance in these tumor cells." (PMID 39666242, 2024). "Intensity of NCF-1 expression in PDAC tissues was comparably weaker than that in gastric cancer tissues, but cytoplasmic staining for NCF-1 was also observed in all 10 cases of invasive pancreatic ductal adenocarcinomas (PDACs) in both tumor nests and inflammatory cells (six representative cases)." (PMID 39666242, 2024). "Here, we report that NCF-1 is expressed not only in inflammatory cells but also in pancreatic and gastric cancer tissues, as well as in related tumor cell lines, observations suggesting that NCF-1 plays a biological role in producing ROS and contributing to tumor cell survival." (PMID 39666242, 2024). "Thus, our results reveal a novel biological aspect of NCF-1 in cancer cells; we expect that further investigation of this phenomenon may contribute to elucidation of the detailed mechanism of ROS and redox regulation in pancreatic and gastric cancers." (PMID 39666242, 2024). "Unlike the conventional role of ROS as a representative cytotoxic factor, these findings suggest that NCF-1-mediated ROS generation may be required for expansive growth of PDAC and gastric cancers." (PMID 39666242, 2024). "Expression of NCF-1 was detected in 14 cases of patient gastric cancer tissues and it seemed not depending on histologic subtypes, although only one out of the total 15 cases (case of por)." (PMID 39666242, 2024).
glioma (1 paper, 2025). A benign or malignant brain and spinal cord tumor that arises from glial cells (astrocytes, oligodendrocytes, ependymal cells). "Furthermore, BMP2, NCF1, HSPB1, PIGT, PTX3, CCNA2, and CCNB2 exhibited increased expression, while DES displayed decreased expression in glioma tissues." (PMID 40656950, 2025).
Hepatic steatosis (1 paper, 2022). Steatosis is a term used to denote lipid accumulation within hepatocytes. "To identify the mechanisms mediating the effect of neutrophil-specific NCF1 on alcohol-induced hepatic steatosis, inflammation, and fibrosis, we performed RNA-Seq analyses of the liver tissues from ethanol-fed WT and Ncf1Lyz–/– mice." (PMID 35838051, 2022). "Our results suggest that the reduction of ROS production secondary to the absence of neutrophilic NCF1 leads to hepatic activation of SIRT1 and AMPK, shifts the intracellular lipid metabolism toward fatty acid oxidation, and ameliorates alcohol-induced hepatic steatosis." (PMID 35838051, 2022).
lung disease (1 paper, 2006). "p47phox/NCF1 pseudogene: wt gene ratio in lung disease and control individuals." (PMID 16608528, 2006).
mastitis (1 paper, 2016). Inflammation of breast tissue during lactation or postpartum due to an obstructed duct or infection. "Two splice variants of NCF1 were sharply up-regulated in the mammary tissues, blood, and neutrophils of mastitis-infected cows compared with those of healthy cows." (PMID 27459697, 2016).
Mediterranean fever (1 paper, 2015). "The G protein-coupled receptor (Hrh4), as well as, Mediterranean fever (Mefv), the inducible heme oxygenase-1(Hmox1) and the Neutrophil cytosol factor 1 (Ncf1) were hubs in the network associated with inflammatory responses." (PMID 25902940, 2015).
mycobacterial infection (1 paper, 2017). "Along the same line of high IL-1β levels found in Ncf1-/- mice reported in this study, those results underscore the importance of the redox regulation of the acute inflammation cytokine IL-1β in mycobacterial infection in the lung." (PMID 29228045, 2017). "Indeed, we found that neutrophils, which are more abundant in the Ncf1-/- mice with mycobacterial infection, produced more IL-1β and the protease NE in neutrophils was capable of processing pro-IL-1β." (PMID 29228045, 2017). "To determine the control of mycobacterial infection in WT and Ncf1-/- mice, we measured the colony-forming unit (CFU) of M. marinum in the whole lung homogenates and found that WT mice gradually controlled mycobacterial growth, whereas the mycobacteria continued to grow in Ncf1-/-mice." (PMID 29228045, 2017).
myeloproliferative disease (1 paper, 2015). "Mice congenitally deficient in nicastrin, a nonredundant Notch-activating protease, develop a malignant myeloproliferative disease dominated by cells expressing elevated levels of transcription factors that control myeloid-specific genes such as Ncf1, cFms and Fcrg29." (PMID 26194095, 2015).
non-Hodgkin lymphoma (1 paper, 2025). Distinct from Hodgkin lymphoma both morphologically and biologically, non-Hodgkin lymphoma (NHL) is characterized by the absence of Reed-Sternberg cells, can occur at any age, and usually presents as a localized or generalized lymphadenopathy associated with fever and weight loss. "Similar to NCF1 and MMP-9, VDR is linked to modulation of immune cell function and considered a specific marker for HL, but not of B-cell derived non-Hodgkin lymphoma." (PMID 41296384, 2025).
prion disease (1 paper, 2012). A transmissible disease that is caused by a protein that is able to induce abnormal folding of normal cellular proteins, leading to characteristic spongiform brain changes, which are associated with neuronal loss without an inflammatory response. "The possible mechanistic links of the remaining genes in the SCC (TLR2, NCF1, PTPN6 and B2M) to prion disease are still open." (PMID 23068602, 2012).
renal agenesis (1 paper, 2024). Renal agenesis (RA) is a form of renal tract malformation characterized by the complete absence of development of one or both kidneys (unilateral RA or bilateral RA respectively), accompanied by absent ureter(s). "Specifically, CD8+ T cells (NCF1) were found to be potentially more crucial in the progression of renal angiomyolipoma and unilateral renal agenesis." (PMID 38872260, 2024).
renal clear cell carcinoma (1 paper, 2021). "In our study, NCF1, NCF2, and NCF4 showed a high expression in renal clear cell carcinoma." (PMID 34708124, 2021).
retinal disease (1 paper, 2020). "The retinal disease score and histology results are consistent and reveal that the absence of Ncf1 decreases EAU severity in mice." (PMID 32380695, 2020).
rheumatic diseases (1 paper, 2023). "The mutation rate of NCF1 rs201802880 in the DAS28M and DAS28H groups was higher than that in the DAS28L group, indicating that missense mutation of NCF1 rs201802880 may be related to both susceptibility to rheumatic diseases and disease activity." (PMID 37138305, 2023).
sarcoma (1 paper, 2015). A usually aggressive malignant neoplasm of the soft tissue or bone. "We found the sarcomas initiated by MCA to develop in a similar manner in both NCF1*/* and NCF1*/+ mice." (PMID 26076008, 2015). "Tregs have previously been implicated in suppressing anti-tumor immunity, and in our MCA induced sarcoma model accumulation of high percentages of Tregs in both NCF1*/* as well as NCF1*/+ mice was found while NOX2 was not key in regulation of tumorigenisis." (PMID 26076008, 2015). "Although a slight trend towards increased tumor take of sarcomas transplanted from NCF1*/* mutant mice was observed, this difference was not significant and did not support a role for NOX2 produced ROS in immune editing of MCA induced sarcomas." (PMID 26076008, 2015). "MCA-sarcomas induced a comparable increase of splenic MDSC in both NCF1*/* and NCF1*/+ mice." (PMID 26076008, 2015). "Since we could confirm that monocytic cells from NCF1*/* mice, in contrast to those from NCF1*/+ mice, were incapable of producing superoxide when stimulated, this argues against NOX2 derived ROS having a major role in MCA induced sarcoma development." (PMID 26076008, 2015). "Furthermore, we observed a sarcoma-induced accumulation of MDSC and Tregs irrespective of the NCF1 mutational status." (PMID 26076008, 2015).
skin infection (1 paper, 2023). An inflammatory process affecting the skin, caused by bacteria, viruses, parasites, or fungi. "NADPH oxidase activity is crucial for control of staphylococcal infections as shown by the fact that mice lacking components of the NADPH oxidase complex, p47phox (Ncf1) or p91phox (Cybb or Nox2), are susceptible to spontaneous skin infections by S. xylosus." (PMID 37533118, 2023).
skin melanoma (1 paper, 2014). "For skin melanoma, somatic mutations in four genes were significantly enriched in their protein pocket regions, including CRP (P = 2.2 × 10-6), NCF1 (P = 6.3 × 10-4), EPO (P = 2.2 × 10-3), and RWDD1 (P = 2.2 × 10-3)." (PMID 25360158, 2014).
stable angina (1 paper, 2022). "For example, the unique targets for stable angina include CASP7 and SLC2A4, while the target for unstable angina is NCF1." (PMID 35140797, 2022).
ulcers (1 paper, 2014). "The Ncf1* mice equally presented ulcers with re-epithelialization, however the epithelial regeneration showed nuclear atypia and low focal dysplasia." (PMID 24873968, 2014).